HLA-E (major histocompatibility complex, class I, E)
Diseases named in the same sentence as HLA-E in open-access papers (continued):
Sharing a sentence is not in itself a finding about the gene and the disease.
myeloma (21 papers, 2011 to 2025). "Human leukocyte antigen-E (HLA-E) has been putatively associated with the pathogenesis of multiple myeloma (MM)." (PMID 34178656, 2021). "Multiple solid and haematological malignancies have been observed to over-express HLA-E and associations between high HLA-E expression and worse clinical outcome have been reported in cancers including ovarian carcinoma, glioblastoma, gastric cancer and multiple myeloma." (PMID 36560403, 2022). "Studies indicate a correlation between elevated HLA‐E expression levels and unfavorable clinical outcomes in different cancer types, such as glioblastoma, ovarian carcinoma, multiple myeloma, vulvar squamous cell carcinoma, and gastric cancer." (PMID 39623605, 2024). "Our findings are consistent with those of previous studies showing that disruption of NKG2A, by protein expression blockers or CRISPR/Cas9, results in improved antitumor activity of NK cells against HLA-E+ Ewing sarcoma and multiple myeloma, respectively." (PMID 37675109, 2023). "The cytotoxic capacity of these genetically engineered NK cells remained even after co-culture with IFNγ pre-treated myeloma cells with increased HLA-E expression." (PMID 36560403, 2022). "Although HLA-E was low on our myeloma cell lines, its expression was increased on primary myeloma cells." (PMID 30542346, 2018). "Inhibition by HLA-class I and HLA-E was also observed with IL-2-activated NK cells and at low oxygen levels (0.6 %) mimicking hypoxic bone marrow niches where myeloma cells preferentially reside." (PMID 25920521, 2015). "Here, we aimed to refine NK cell therapy by evaluation of the relevance of HLA-class I and HLA-E for NK anti-myeloma reactivity." (PMID 25920521, 2015). "In the present study, aimed to refine the selection process for NK cell therapy, we studied the relevance of HLA-class I and HLA-E for anti-myeloma reactivity of allogeneic NK cells." (PMID 25920521, 2015). "In our quest of further refining NK cell therapy, we evaluated the clinical relevance of HLA-class I and HLA-E for the anti-myeloma response of alloreactive NK cells." (PMID 25920521, 2015). "In a co-culture system allowing the synchronized analysis of degranulation of NK cell subsets, we identified HLA-E as a potent inhibitory factor for anti-myeloma reactivity of NK cells expressing the inhibitory NKG2A receptor." (PMID 25920521, 2015). "As we observed a clear expression of HLA-E on all patient-derived CD38high cells, but only low expression on in vitro cultured myeloma cell lines, we compared HLA-E expression on in vitro grown U266 cells with U266 cells after in vivo passaging." (PMID 25920521, 2015). "First, we determined the presence of HLA-class I and HLA-E on primary myeloma cells and on myeloma cell lines, revealing that primary myeloma cells express both HLA-class I and HLA-E." (PMID 25920521, 2015). "Surface expression of HLA-class I and HLA-E was also assessed on a panel of myeloma cell lines including U266, L-363, LME-1, UM-9, RPMI-8226/S, OPM-1 and XG-1, and on the leukemia cell line K562." (PMID 25920521, 2015). "Interestingly, during NK cell expansion, NKG2A is significantly upregulated, and high HLA-E expression on multiple myeloma cells can limit CAR-NK cell function, which can be restored with NKG2A blockade." (PMID 40291981, 2025). "The study showed that s-μg (horizontal axis rotation) decreased subsequent NK-cell cytotoxic function in 1g against allogeneic target cell lines of leukemia (K562 cell line), multiple myeloma (U266 cell line), B-lymphoma (721.221), and HLA-E transfected lymphoma (221." (PMID 38255998, 2024). "Moreover, induction of ER stress by bortezomib renders myeloma cell lines sensitive to NK cells due to downregulation of surface HLA-E, potentially via decreased peptide loading." (PMID 36560403, 2022). "Additionally, dexamethasone initiates an NK cell immune response by downregulation of HLA-E surface expression on multiple myeloma cell lines." (PMID 36560403, 2022).
myeloma (continued). "As mentioned, the results show that HLA-E was highly expressed on myeloma cells." (PMID 34178656, 2021). "CD138+HLA-E+ and CD138+HLA-E- myeloma cells were cultured with peptide M and P3." (PMID 34178656, 2021). "Based on the results, PEPTIDE 3 could markedly increase the bonding affinity, indicating that it was a potential peptide drug candidate for targeting HLA-E in myeloma." (PMID 33115963, 2020). "Correlation of seropositivity for CMV with increased expression of activating receptor NKG2C has previously been described, with NKG2C+ impacting cytotoxicity on HLA-E expressing cells such as haematological malignancies which have been shown to affect myeloma cells." (PMID 30759167, 2019). "NKG2A is known to interact with HLA-E and is known to be increased on myeloma cell lines." (PMID 30542346, 2018). "In all myeloma patients, CD38high cells were positive for HLA-E and HLA-class I." (PMID 25920521, 2015). "HLA-E was highly expressed by primary myeloma cells but only marginally by cell lines." (PMID 25920521, 2015). "Thus, the present study aims to continue our investigation on the clinical meaning of HLA-E expression in MM patients and further explore whether peptide P3 could target HLA-E positive myeloma cells." (PMID 34178656, 2021). "Therefore selinexor mediated HLA-E downregulation may have broad relevance for activation of NK cells against solid tumors and multiple myeloma, in addition to lymphoma." (PMID 34926302, 2021). "This indicates that HLA-E could be considered as a marker for predicting whether the patients have high-risk myeloma or not." (PMID 34178656, 2021). "Additionally, our findings suggest that neutrophils in myeloma patients engage in aberrant interactions with NK cells via receptors such as HLA-E, which could account for the diminished NK cell presence in the high-risk cohort, consequently affecting prognosis." (PMID 38278930, 2024). "We demonstrate that HLA-E expression is present in pre-malignant plasma cell disorders (monoclonal gammopathy of undetermined significance – MGUS and smoldering multiple myeloma – SMM) and in overt MM." (PMID 38902472, 2024). "We analyzed the morphology of the patient primary myeloma cells for expression levels of MHC I, MICA, MICB, ULBP1, ULBP2/5/6, HLA-E, CD38 (n = 12), CD112, CD155, ICAM-1 and PD-L1 (n =5) using flow cytometry." (PMID 35413499, 2022). "HLA-E is frequently overexpressed in solid tumors and hematological malignancies including CLL and multiple myeloma." (PMID 34926302, 2021). "The proteasome inhibitor bortezomib can downregulate HLA-E, the ligand for the inhibitory NKG2A receptor, and increase surface expression of death receptors on cancer cells to promote NK cell cytotoxicity against multiple myeloma cells." (PMID 40291981, 2025). "Autologous CIK immunotherapy can also address the high expression of inhibitory HLA-E on myeloma cells, due to the absence of expression of CD94/NKG2A on CIK cells." (PMID 35413499, 2022). "The most striking observation in our study was that the HLA-E level on U266 cells grown in the BM of RAG-2−/−γc−/−mice was considerably higher than the level on in vitro cultured U266 and was relatively comparable to the expression levels in myeloma patients." (PMID 25920521, 2015). "This makes HLA-E clinically highly relevant, but information on HLA-E expression and its inhibitory potential in myeloma is lacking." (PMID 25920521, 2015). "This phenomenon was also valid for targeting myeloma in a hypoxic environment of 0.6 % oxygen, showing that degranulation of activated NK cells was not severely hampered by the low levels of HLA-E present on the myeloma cell lines." (PMID 25920521, 2015). "HLA-E expression, on the other hand, was lower on cell lines than on primary myeloma cells and ranged from completely absent, e.g., on OPM-1, to very low on most of the other myeloma lines." (PMID 25920521, 2015).
myeloma (continued). "Expression of HLA-E in primary myeloma has not been reported, and the present study shows that HLA-E is indeed expressed by CD38high cells of myeloma or PCL patients." (PMID 25920521, 2015). "The level of HLA-E and HLA-class I on CD38high cells was comparable to the level observed on normal BM cells of the same patient or on plasma cells from a non-myeloma patient (data not shown)." (PMID 25920521, 2015). "Concurrent analysis of inhibitory receptors (KIR2DL1, KIR2DL2/3, KIR3DL1 and NKG2A) and NK cell degranulation upon co-culture with myeloma cells revealed that KIR–ligand-mismatched NK cells degranulate more than matched subsets and that HLA-E abrogates degranulation of NKG2A+ subsets." (PMID 25920521, 2015). "While it was known that IFN-γ via STAT1 could increase HLA-E levels, we here indisputably prove that CREB1 and STAT1 both contribute to HLA-E expression in myeloma, with CREB1 binding to HLA-E promoter and CREB1 inhibitors decreasing HLA-E expression in cell lines and patient samples." (PMID 38902472, 2024). "It was found that both peptide M and P3 could interact with CD138+HLA-E+ cells but not with CD138+HLA-E- myeloma cells." (PMID 34178656, 2021). "However, in a previous study with the same experimental setup, we showed that high HLA-E levels in multiple myeloma cells inhibited NK cells, while low HLA-E levels were not sufficient to do so." (PMID 34203549, 2021). "Hence, although HLA-E is not the only contributing factor, our data show that HLA-E can clearly inhibit the anti-myeloma response of KIR-NKG2A+ NK cells." (PMID 25920521, 2015).
autoimmune disease (19 papers, 2009 to 2026). A disorder resulting from loss of function or tissue destruction of an organ or multiple organs, arising from humoral or cellular immune responses of the individual to their own tissue constituents. "In the current review, we aimed to uncover the reason of the expansion of the younger allele, HLA-ER, by analysis of associations of both HLA-E alleles with a number of diseases, including viral and bacterial infections, cancer, and autoimmune disorders." (PMID 31690066, 2019). "To analyze the reason for this, we will review the HLA-E alleles association with the different diseases, including viral and bacterial infections, cancer, and autoimmune disorders, in the sections below." (PMID 31690066, 2019). "Furthermore, HLA-E*0103 allele has been associated with high levels of soluble HLA-E (sHLA-E), which provides protection against NK-mediated lysis and usually correlates with disorders such as cancer and autoimmune diseases." (PMID 33375572, 2020). "For example, it has been shown that an important role of Qa-1-restricted (HLA-E in humans) CD8+ Tregs is to prevent autoimmune disease in adult mice by suppression of follicular helper T cells." (PMID 36466865, 2022). "Expression of HLA-E is often detected on cells of different tissues in pathologic conditions, such as cancer, bone marrow transplantation, and autoimmune diseases." (PMID 31690066, 2019). "In this regard, potential HLA-E-restricted CD8+ T cells were observed in patients with several human autoimmune diseases such as MS and type 1 diabetes." (PMID 31569411, 2019). "Future research on the role of regulatory NK cells may help to fabricate and develop desirable therapeutic approaches to manage autoimmune diseases in a more targeted fashion, such as masking HLA-E on CD4+ T cells to kill activated autologous T cells." (PMID 37275764, 2023). "These defined functions of the anti-HLA-E IgG2a mAbs at a level superior to IVIg encourage developing their humanized version to lower antibodies in allograft recipients, to promote graft survival, and to control autoimmune diseases." (PMID 28634589, 2017). "This, in turn, could lead to an imbalance of the inhibitory function of HLA-E on natural killer (NK) activity or to an alteration of regulatory functions as it has been shown in animal models of autoimmune diseases." (PMID 19912639, 2009). "Analysis of autoimmune disorders has revealed that CD8 T regulatory cells (CD8 Tregs) inhibit pathogenic responses through recognition of self-peptides associated with MHC class Ia or class Ib (MHC-E: mouse Qa-1 and human HLA-E) expressed by target CD4+ T helper cells." (PMID 37934601, 2024). "It is important to note that the ligand-receptor system of HLA-E and NKG2A/B seems to play the considerable role in a number of autoimmune diseases, including rheumatoid arthritis, ankylosing spondylitis, and psoriasis." (PMID 31690066, 2019). "Overall, this study identifies a novel mechanism of resistance of B cells to NK cell cytotoxicity and indicates that blockade of the HLA-E:NKG2A and HLA:KIR checkpoint axes could be beneficial for improving B-cell depletion in patients with autoimmune diseases." (PMID 41528734, 2026).
glioblastoma (17 papers, 2011 to 2025). The most malignant astrocytic tumor (WHO grade IV). "In line with this, increased HLA-E expression was linked to extended survival for several human tumors, including cervical adenocarcinomas and glioblastomas." (PMID 41347075, 2025). "Glioblastoma tumour cells often upregulate HLA-E, and most glioblastoma tumours express HCMV peptides, which can trigger their recall memory response." (PMID 41194660, 2025). "It was noted that in glioblastoma cell line modified with HLA-E*spG, the NKG2C+ NK cells showed significantly increased cytotoxicity towards them, compared to the parental cells." (PMID 36899273, 2023). "The cytotoxic profile of NKG2C+ NK cells was upregulated against glioblastoma multiforme cells and altering these cells by the HLA-E*spG feeder cells only enhanced this effect." (PMID 36899273, 2023). "In summary, the data indicate that activation through NKG2C is involved in the subtle tuning of NK cell reactivity towards glioblastoma cells expressing HLA-E and HLA-G." (PMID 35628668, 2022). "In our study, we corroborated for the first time, a natural and specific cytotoxicity of NKG2C+ NK cells towards HLA class I-positive glioblastoma cells expressing HLA-E and HLA-G." (PMID 35628668, 2022). "NKG2C+ NK cells exhibited natural cytotoxicity against HLA-ABC+/HLA-E+/HLA-G+ primary glioblastoma cells which was increased by KIR:HLA mismatch, whereas corresponding fresh NK cells from peripheral blood and NKG2A+ NK cells showed no cytotoxic response." (PMID 35628668, 2022). "As for glioma, HLA-E has been reported to be elevated in human glioblastomas by immunohistochemistry, which was in consistent with what we demonstrated by microarray analysis in this study." (PMID 32066399, 2020). "Strong HLA-E:NKG2C ligation can contribute to recognition and killing of glioblastoma cells by NK cells." (PMID 39498293, 2024). "In particular, in glioblastoma the expression of both HLA-E and HLA-G might be exploited for an immunotherapy with adaptive NKG2C+ NK cells, which specifically recognize HLA-E molecules presenting a high affinity peptide derived from HLA-G." (PMID 35628668, 2022). "In glioblastoma, non-classical human leucocyte antigen E (HLA-E) and HLA-G are frequently overexpressed." (PMID 35628668, 2022). "Moreover, ectopic overexpression of HLA-E*spG on target cells further enhanced the cytotoxic response of NKG2C+ NK cells, demonstrating that strong HLA-E:NKG2C ligation can contribute to recognition and killing of glioblastoma cells by NK cells." (PMID 35628668, 2022). "The NK-mediated killing of glioblastoma cells (GBM) has been identified by the low levels of HLA class I both classical (HLA-A, -B, -C) and non-classical (HLA-E) molecules and by the expression of DNAM-1 and NKp46 activating NK receptors." (PMID 27242786, 2016).
gastric cancer (16 papers, 2016 to 2025). A primary or metastatic malignant neoplasm involving the stomach. "Increased soluble HLA-E concentration was associated with disease susceptibility in various disorders, including chronic hepatitis B, juvenile idiopathic arthritis, and gastric cancer." (PMID 37901227, 2023). "In addition, clinical factors associated with gastric cancer are independently influenced by HLA-E and HLA-F." (PMID 36923953, 2023). "HLA-E and NK cell status serve as a sensitive prognostic factor in advanced gastric cancer, whilst HLA-E expression was identified as a major regulator of tumour cell susceptibility to NK cell lysis." (PMID 36560403, 2022). "Another study demonstrated that overexpression of HLA-E was related to a lower five-year survival rate in patients with gastric cancer." (PMID 32066399, 2020). "Studies have suggested that the combined assessment of HLA-E expression in tumors, immune cells, and antigen-presenting cells, along with NK cell levels, could provide an effective prognostic tool for advanced gastric cancer patients." (PMID 39845968, 2024). "For example, increasing soluble HLA-E contributes to immune escape in gastric cancer (GC) cell lines." (PMID 41440003, 2025). "A study in gastric cancer also indicated that NK cell status, combined with HLA-E expression, can serve as a prognostic factor for evaluating recurrence-free survival (RFS) in advanced gastric cancer patients." (PMID 39845968, 2024). "We could not find the gene expression data for HLA-E and thyroid cancer with BRAF mutation in other studies, but HLA-E and HLA-F expression significantly correlated with depth of invasion, nodal involvement, lymphatic invasion, and venous invasion in gastric cancer patients." (PMID 36975440, 2023).